IL6 (interleukin 6)
Diseases named in the same sentence as IL6 in open-access papers (continued):
Sharing a sentence is not in itself a finding about the gene and the disease.
periodontal disease (340 papers, 2007 to 2026). "Cortisone correlated strongly with cortisol (ρ = 0.523, p < 0.001) and was positively associated with IL-6 (ρ = 0.322, p = 0.008) and multiple clinical indicators of periodontal disease severity." (PMID 41596453, 2026). "In periodontal diseases, models overexpressing IL-6 or TNF-α mimic inflammatory bone loss, while MMP-9 knockout mice display reduced periodontal degradation." (PMID 41559024, 2026). "The median values, interquartile ranges, and outliers depicted in the boxplots visually reinforce the diagnostic potential of both salivary IL-6 and irisin as biomarkers for periodontal disease severity." (PMID 41007333, 2025). "This study aims to establish the association of salivary IL-6 levels with COVID-19 and periodontal disease status in unvaccinated patients who underwent COVID-19 testing during the acute phase of the pandemic in 2020 and 2021." (PMID 40647649, 2025). "For instance, research indicates that periodontal disease is associated with elevated systemic inflammatory markers, including IL-6 and TNF-α." (PMID 40243946, 2025). "Given the inflammatory nature of periodontal diseases, gingivitis is also linked to increased levels of salivary inflammatory cytokines, including IL-6, TNF-α, IL-1β, IL-8, and IL-10." (PMID 40243684, 2025). "Periodontal disease is associated with elevated inflammatory biomarkers, including IL-1, IL-6, TNF-α, and CRP, which are also elevated in AD." (PMID 40559320, 2025). "This inflammation is associated with increased levels of interleukin-6 (IL-6), a cytokine upregulated during periodontal disease as part of the host response to bacterial challenge." (PMID 41007143, 2025). "Various pro‐inflammatory mediators, such as NO and IL‐6, are present at a high level in the lesion site of periodontal disease and are associated with a higher severity of periodontal disease." (PMID 40761494, 2025). "The results suggest that IL-6 and irisin serve not only as diagnostic salivary biomarkers but also as active participants in the molecular pathogenesis of periodontal disease." (PMID 41007333, 2025). "The chronic inflammation associated with periodontal disease results in the release of pro-inflammatory cytokines such as interleukin-1 (IL-1), interleukin-6 (IL-6), and tumor necrosis factor-alpha (TNF-α)." (PMID 40283848, 2025). "A review discussed the role of IL-6 in oral diseases, noting that elevated IL-6 levels are associated with conditions such as periodontal disease and oral cancer." (PMID 40243946, 2025). "For instance, vitamin D has been shown to reduce the expression of cytokines linked to periodontal disease and dementia, such as interleukin-6, interleukin-8, and tumor necrosis factor-α." (PMID 40907543, 2025). "Studies have indicated an association between the IL-6-572GG genotype and periodontal disease, e.g., chronic periodontal disease in Caucasian, Chinese and Japanese populations, as well as aggressive periodontitis." (PMID 38396821, 2024). "Moderate periodontal disease was positively associated with IL-6 levels after controlling for potential confounding factors." (PMID 39062000, 2024). "One of the most prominent is IL-6, which has been associated with periodontal disease progression in susceptible patients." (PMID 39215289, 2024). "Hypomethylation of interleukin-6 and interleukin-8 gene promoters has been linked to overexpression of these cytokines in inflamed periodontal disease tissues compared to control tissues." (PMID 38575895, 2024). "Gingivitis is an inflammation of the gums that is the initial cause of the development of periodontal disease by the activity of Nuclear Factor-kappa B (NF-κB), Interleukin-1β (IL-1β), Interleukin-6 (IL-6), p38, and Tumor Necrosis Factor-α (TNF-α)." (PMID 38978754, 2024).
periodontal disease (continued). "A large body of experimental evidence suggests that the presence of the G allele, and thus the increased expression of IL6, is associated with periodontal disease, inducing osteoclast differentiation and bone resorption and inhibiting bone formation." (PMID 39451399, 2024). "Periodontal disease can cause low-grade systemic inflammation, which can elevate the level of inflammatory mediators such as IL-1, IL-6 and C-reactive protein." (PMID 36985292, 2023). "IL-6 is another important pro-inflammatory cytokine implicated in the progression of periodontal disease." (PMID 37629104, 2023). "In in vivo studies, systemic low-grade inflammation after experimental periodontal disease was associated with increased gene expression for adipose tissue levels of interleukin (IL)-6 and C-reactive protein (CRP) in a rat model." (PMID 36767065, 2023). "The presence of periodontal disease and/or cancer also increases IL-6 in PB, which would be associated with cancer progression." (PMID 35804048, 2022). "Periodontal diseases increase levels of circulating IL-1β, IL-6, IL-8, IL-17 and TNF-α, interleukins associated with systemic inflammation and preterm birth." (PMID 35369278, 2022). "It was also suggested that the presence of periodontal disease and/or cancer also increases IL-6 in PB, which would be associated with cancer progression." (PMID 35804048, 2022). "Homeostatic oral Th17 cells are commensal-independent and IL-6-dependent, whereas the development and maintenance of Th17 cell-associated periodontal diseases is largely dependent upon the local microbiomes and require a pro-inflammatory microenvironment." (PMID 35222410, 2022). "A recent systematic review evaluated macrophage inflammatory protein-1α (MIP-1α), IL-1β, IL-6 and MMP-8 as diagnostically acceptable biomarkers for periodontal disease, and the combination of IL-6 and MMP-8 showed the best diagnostic performance." (PMID 35562715, 2022). "Conversely, the periodontal diseases are correlated to associated to a Th2 cell-mediated and an overexpression of the IL-4, IL-5, IL-6, and IL-10 mediators." (PMID 35735643, 2022). "As for C5, it was reported that C5a can induce the activation of C5Ar in a murine periodontal disease and cause significant bone loss with the help of cytokines like IL-17, IL-1β, IL-6, and TNF." (PMID 35571048, 2022). "The elevated production of tumor necrosis factor‐α, IL‐1β, and IL‐6 have also been observed in patients with periodontal disease, which further leads to PDL destruction and attachment loss." (PMID 33270996, 2021). "Individuals with CP have higher risk to develop periodontal disease due to reduced salivary flow rate, increased salivary osmolality rate and elevated TNFα, IL-10, IL-6 compared to DS." (PMID 32509226, 2020). "Individuals with cerebral palsy present higher risk to develop periodontal disease due to the reduced salivary flow rate, increased salivary osmolality rate and elevated levels of TNFα, IL-10, IL-6 compared to individuals with individuals with Down syndrome." (PMID 32509226, 2020). "Although the expression of proinflammatory cytokines associated with periodontal disease pathogenesis (such as, IL-1β, IL-6, IL-17A, and TNF) was inhibited, statistical significance was reached only for IL-17A, which was downregulated by 4.9-fold." (PMID 31581596, 2019). "A mouse model of alveolar bone loss induced by periodontopathic bacteria Porphyromonas gingivalis showed that CD4+ T cell-derived IFNγ and IL-6 were important effectors of bone loss associated with periodontal disease." (PMID 30158833, 2018). "In RAW macrophages, PBMCs and transgenic mice, the IL37 variant increases expression of IL-1β and IL-6, inducing more severe periodontal disease, while IL-37 protein production is impaired and shows reduced cleavage by caspase-1." (PMID 30206230, 2018).
periodontal disease (continued). "We also aimed to analyse the association between the severity of the periodontal disease in diabetic patients and the increase in interleukin levels (IL-6, IL-1β and PGE2)." (PMID 29075409, 2017). "Although the association between IL-6 and IL-10 with periodontal disease initiation has been supported extensively in the literature, the findings of this study can confirm the lack of effect of IL-6 and IL-10 on the resolution of periodontal inflammation." (PMID 28624837, 2017). "IL-6 -572 G/C polymorphisms lead to an increase in the expression of IL-6, which plays a key role in the susceptibility to periodontal disease." (PMID 28624837, 2017). "The selected sample was evaluated for the periodontal disease association with IL6 c.-174G>C gene polymorphism." (PMID 25548674, 2014). "One of the well-studied cytokines genes whose variants are associated with periodontal disease occurrence is interleukin-6." (PMID 25548674, 2014). "The present survey showed that the prevalence of CKD was 18.2% in patients with periodontal disease, with low awareness of 16.2%, and inflammation markers (IL-6, hsCRP or TNF-α) are special risk factors for CKD in this population." (PMID 23951003, 2013). "Bacterial pathogens causing periodontal disease incite the secretion of inflammatory mediators, including IL-6, TNF-α and CRP." (PMID 23951003, 2013). "Several studies have shown a relationship between periodontal disease and genetic factors, including polymorphisms in interleukin (IL)-1, interferon-γ, IL-6, matrix metalloproteinase (MMP)-9, tissue inhibitor of MMP-2, vitamin D receptor, IL-1α, and IL-1β." (PMID 23050158, 2012). "It is hypothesized that an increase in irisin levels could potentially mitigate the inflammatory effects of visfatin and IL-6, suggesting a possible protective mechanism against the systemic inflammation often associated with periodontal disease." (PMID 41280712, 2025). "With more precise testing methods in the future, the identification and detection of salivary irisin, visfatin, and IL-6 may serve as potential biomarkers to predict susceptibility to periodontal diseases." (PMID 41280712, 2025). "Adipose tissue releases pro- and anti-inflammatory cytokines and hormones such as irisin, visfatin, and interleukin-6, which may be linked to periodontal diseases." (PMID 41280712, 2025). "Periodontal disease has been associated to increased levels of cytokines, including IL-6 production which could in turn amplify the mechanism." (PMID 39884984, 2025). "Elevated levels of C-reactive protein and pro-inflammatory cytokines like TNF-α and IL-6 induced by periodontal disease are linked to systemic disorders and could indirectly affect both the lungs and the brain." (PMID 38909262, 2024). "As a result of periodontal disease, pathogenic bacteria may move from the periodontal pocket to the blood, causing the release of interleukin (IL)-6, which probably starts a chain of events resulting in systemic bone resorption." (PMID 38511766, 2024). "In particular, IL1β and IL-6 have shown to be elevated in subjects with periodontal disease, although both pro-inflammatory and anti-inflammatory cytokines have also been implicated in periodontal disease." (PMID 36319939, 2023). "Previous studies have shown that elevated levels of serum inflammatory markers, such as tumor necrosis factor-α, interleukin-6, interleukin-2, and C-reactive protein, are associated with an increased risk of AF and are commonly found in patients with periodontal disease." (PMID 37420240, 2023). "Furthermore, in T2DM there is an increase in TNF-α, IL-1β, IL-6, and IL-18, which are known to elevate HbA1C, which increases the risk for periodontal disease." (PMID 37629193, 2023). "Additionally, recent research has linked IL-6 to the progression of periodontal disease and the exacerbation of tissue degradation." (PMID 38239915, 2023).
periodontal disease (continued). "Sub-gingival plaque and saliva-serum cytokine levels were measured in patients with OSA in a study; OSA was found to be associated with worsening periodontal disease and greater amounts of IL-6 and apelin in the saliva, as well as changed the bacteria that were examined in plaque." (PMID 37803323, 2023). "Furthermore, OSA is associated with more severe periodontal disease and higher levels of IL-6 in the saliva and appeared to change the bacteria tested in plaque." (PMID 37803323, 2023). "Several studies also show the relationship between sex hormones and changes in the production of inflammatory cytokines such as tumor necrosis factor, which has been quite associated with periodontal disease, as well as the IL-1 and IL-6, associated with bone resorption." (PMID 33526027, 2021). "Increased salivary IL-6 concentration could both cause and impact periodontal disease in patients with OSAS." (PMID 34205812, 2021). "As a chronic inflammation caused by periodontal pathogen infections, periodontal disease could increase the levels of C-reactive protein, IL-6, IFN-γ, and IL-1β." (PMID 32802852, 2020). "Therefore, we can exclude smoking and periodontal disease as a potential causes of differences between IL-6 and TNF-α serum concentration between men and women." (PMID 25858079, 2015). "The reduction in inflammation in the AAV-sh-Atp6i treatment group may be partially due to the downregulation of CD115 (important for monocyte and macrophage differentiation), and IL-6 (a proinflammatory cytokine associated with periodontal disease)." (PMID 23577057, 2013). "We found that high values of hsCRP and TNF-α level were associated with the albuminuria in patients with periodontal disease; high value of IL-6 level was associated with the reduced eGFR in patients with periodontal disease; high value of TNF-α level were associated with the CKD." (PMID 23951003, 2013). "In addition, periodontitis causes the secretion of cytokines such as TNF-α, IL-1β, and IL-6, leading to systemic inflammation, which may connect periodontal disease to a number of systemic problems, such as cardiovascular and neurological conditions." (PMID 40243684, 2025). "Similarly, a study showed that higher levels of IL-2, IL-6, IL-10, TNF-α, and PGE2 were detected in the serum of preterm women with periodontal disease, while the serum levels of IL-2, IL-6, and IL-10 were higher in high-risk preterm women than in low-risk preterm women." (PMID 36388896, 2022). "However, elevated levels of TNF-α, IL10, IL-6, IL-1β and IL-8 were observed in the CP group, which may increase the susceptibility and progression of periodontal disease in these individuals." (PMID 32509226, 2020). "The associated pathophysiology could be that periodontal disease induces host cells to generate and release pro-inflammatory cytokines such as interleukin-1 (IL-1), interleukin-6 (IL-6), tumor necrosis factor-alpha (TNF-α), and reactive oxygen species (ROS) to induce the development of PD." (PMID 30049978, 2018). "IL-6 and IL-8 are important cytokines involved in the immune responses against infection, but overexpression of these cytokines might cause inflammatory diseases, including periodontal diseases." (PMID 29760819, 2018). "In periodontal diseases, MMP-9 and IL-6 play roles in inflammatory-driven bone loss, while TNF-α and TRAP (ACP5) are implicated in osteoclast activation." (PMID 41559024, 2026). "These cytokines include interleukin-1 beta, interleukin-6, and tumour necrosis factor alpha, which are established biomarkers for periodontal diseases." (PMID 40310396, 2025). "Targeting these shared axes—whether through the modulation of autophagy, inhibition of TNF or IL-6 signaling, or fine-tuning of Wnt pathways—represents a promising translational strategy for controlling chronic inflammation and preventing bone loss in periodontal disease." (PMID 41155385, 2025).
periodontal disease (continued). "Elevated visfatin levels can lead to increased IL-6 release, creating a cycle of inflammation that exacerbates periodontal disease." (PMID 41280712, 2025). "A three-group meta-analysis showed that immunotherapy affected periodontal disease progression by modulating local immune factors IL-1β, IL-17, IL-6, IL-8 and TNF-α, thus providing a potential statistically significant benefit." (PMID 41356100, 2025). "The cytokine profile observed—characterized by significant increases in IL-1β, IL-6, TNF-α, and IL-8—indicates that candidiasis in children is associated with an inflammatory state similar to that observed in early-onset periodontal disease." (PMID 41301927, 2025). "IL-6 and IL-1β are both proinflammatory cytokines with established involvement in periodontal disease pathogenesis and drug induced gingival enlargements." (PMID 40182222, 2025). "Numerous studies on chronic inflammatory conditions, particularly periodontal diseases, have reported elevated IL-6 levels and demonstrated their correlation with disease severity." (PMID 41007333, 2025). "Periodontal disease severity showed moderate associations with both circulating hs-CRP and IL-6 in the univariate analysis, but only IL-6 association was confirmed after adjusting for confounders." (PMID 40952033, 2025). "As a reaction to the presence of bacteria in periodontal diseases, a variety of immune cells such as monocyte and dendritic cells are activated to phagocytose bacteria and produce inflammatory mediators including IL-6." (PMID 40097880, 2025). "Both OSAS and periodontal disease exhibit shared inflammatory pathways, particularly characterized by elevated levels of inflammatory markers, including interleukin-6 (IL-6) in saliva." (PMID 40807223, 2025). "Future preclinical and clinical investigations are warranted to assess the safety and efficacy of IL-6 -targeted therapies as adjuncts in periodontal disease management." (PMID 41007333, 2025). "Previous studies have shown that periodontal disease is caused by bacteria present in dental plaque, which induce the production of inflammatory cytokines, such as TNF-α, IL-1β, and IL-6, thereby forming a cytokine cascade." (PMID 41303285, 2025). "(2024) successfully demonstrated significant reductions in TNF-α and IL-6 at 8 weeks in diabetic patients with periodontal disease." (PMID 41244040, 2025). "According to some studies, serum levels of IL-6 are higher in patients with periodontal disease than in healthy controls." (PMID 39758261, 2024). "Cytokines, including IL-1A, IL-1B, IL-10, and IL-6, released during gastrointestinal disturbances, are pivotal in driving the inflammatory response in periodontal disease." (PMID 39200318, 2024). "For instance, impairment in glucose tolerance is associated with a significant increase in the interleukin-6 and CRP levels, and the prevalence of periodontal disease in patients with DM was found to be higher than that of healthy controls." (PMID 39453923, 2024). "An in vitro modeling of periodontal disease points out that MF alleviates inflammatory response by inhibiting the expression of interleukin-6 (IL-6) and activation of Toll-like receptor (TLR) signaling." (PMID 39202505, 2024). "IL-6 is considered a marker for periodontal disease activity, most likely a consequence of systemic disruption of bacteria or bacterial products." (PMID 38627806, 2024). "Periodontal disease triggered an increase in inflammatory cytokines (IL-6, TNF-α) in the uterus, which was abrogated by nisin treatment." (PMID 39203489, 2024). "The mRNA levels of IL-6 and IL-1β are elevated in tissues affected by both periodontal disease and peri-implantitis." (PMID 39650553, 2024). "Taking this fact into consideration, elevated IL-6 levels in periodontal disease patients are a possible co-factor accelerating the occurrence of inflammation at other distant sites." (PMID 38396821, 2024).